ADAT1 (adenosine deaminase tRNA specific 1)
Description:
Specifically deaminates adenosine-37 to inosine in tRNA-Ala.
Synonyms: hADAT1
Tractability: PROTAC: ubiquitination databases record sites on it.
Gene: Protein-coding gene on chromosome 16 (75,596,868 to 75,623,300, reverse strand). Ensembl gene ENSG00000065457.
Subcellular location (Human Protein Atlas): Nucleoplasm
Pathways (Reactome):
Metabolism of RNA: tRNA modification in the nucleus and cytosol
Gene Ontology:
Molecular function: RNA binding; tRNA-specific adenosine deaminase activity; adenosine deaminase activity; tRNA-specific adenosine-37 deaminase activity
Biological process: tRNA processing; RNA processing
Cellular component: nucleoplasm
Genetic constraint (gnomAD): Loss-of-function variants: 58 observed, 60.52 expected, observed/expected ratio (o/e) 0.96, 90% interval 0.77 to 1.19. The upper end of that interval is the gene's LOEUF score, 1.19, which puts it in group 5 of 6, group 1 being the genes least tolerant of losing a copy. Missense variants: 736 observed, 638.82 expected, observed/expected ratio (o/e) 1.15, 90% interval 1.08 to 1.22. Synonymous variants: 253 observed, 231.57 expected, observed/expected ratio (o/e) 1.09, 90% interval 0.99 to 1.21.
Homologues: Orthologues: chimpanzee ADAT1 (99% identical), macaque ADAT1 (94% identical), pig ADAT1 (81% identical), guinea pig ADAT1 (81% identical), rabbit ADAT1 (81% identical), rat Adat1 (78% identical), mouse Adat1 (78% identical), dog ADAT1 (73% identical), tropical clawed frog adat1 (50% identical), zebrafish adat1 (45% identical), Caenorhabditis elegans adr-1 (20% identical), Caenorhabditis elegans D2005.1 (18% identical), and 2 more. Paralogues in human: ADAR (26% identical), ADARB2 (25% identical), ADARB1 (23% identical), ADAD1 (20% identical), ADAD2 (19% identical), ILF3 (12% identical), STRBP (11% identical), STAU1 (10% identical), ZFR (9% identical), STAU2 (9% identical), ZFR2 (9% identical), ILF2 (8% identical), and 2 more.
Diseases named in the same sentence as ADAT1 in open-access papers:
ADAT1 is named in the same sentence as 2 diseases in open-access papers, as found by Europe PMC text mining. Sharing a sentence is not in itself a finding about the gene and the disease. The quoted sentences say what the papers report.
endometriosis (1 paper, 2023). The growth of functional endometrial tissue in anatomic sites outside the uterine body. "Therefore, researchers can investigate whether gene variations or mutations associated with endometriosis involve ADAT1 or related pathways." (PMID 38098472, 2023). "Further experimental evidence and clinical studies are necessary to fully understand the potential role of ADAT1 in endometriosis." (PMID 38098472, 2023). "It is important to emphasize that current literature has not reached definite conclusions about the relationship between ADAT1 and endometriosis." (PMID 38098472, 2023). "Current research indicates no direct or known association between ADAT1 and endometriosis." (PMID 38098472, 2023).
tumor (1 paper, 2020). "The results showed that the expression levels of seven tRNA-modifying genes (FTSJ1, ADAT1, U13, RNMTL1, TRDMT1, METTL14, and TRMT1L) in NSCLC tumor tissues were significantly lower than that in normal tissues (all P values < 0.05)." (PMID 32393790, 2020).